IL6 (interleukin 6)
Diseases named in the same sentence as IL6 in open-access papers (continued):
Sharing a sentence is not in itself a finding about the gene and the disease.
endothelial dysfunction (continued). "In addition, PPIs have been known to cause hypomagnesemia, which is associated with endothelial dysfunction, oxidative stress, mitochondrial dysfunction, decreased nitric oxide production, and the increased synthesis of pro-inflammatory cytokines, IL-6, and TNF-α." (PMID 39061988, 2024). "In term of BCAAs supplementation, a previous study demonstrated that BCAAs could affect the releasing of pro-inflammatory cytokines, such as IL-6, in the inflammatory response, which is associated with the increasing of endothelial dysfunction and arterial stiffness." (PMID 36297014, 2022). "Endothelial dysfunction is prevented by a high antioxidant diet, which is linked to reduced levels of pro-inflammatory cytokines in the plasma Moreover, pro-inflammatory cytokines like IL-6 and TNF- may also suppress BDNF expression." (PMID 34580389, 2021). "Interestingly, pro-inflammatory cytokines, in particular TNFα, IL-6, and IL-18, and adhesion molecules involved in the atherosclerotic process have been associated with endothelial dysfunction, carotid atherosclerosis, CV morbidity and risk of CV events and mortality in patients with systemic ARDs." (PMID 31110500, 2019). "Within the same setting, we sought to further assess whether biomarkers of inflammation (IL–6) and monocyte activation (sCD163) or carotid intima–media thickness (cIMT) were associated with biomarkers of endothelial dysfunction among virally suppressed HIV–infected participants." (PMID 29771268, 2018). "Surprisingly, measurement of Ach-induced vasodilation of pre-constricted aortic rings revealed no impairment of peripheral endothelial function in IL-6−/− mice excluding the presence of endothelial dysfunction in IL-6−/− mice that could predispose them to impaired exercise performance." (PMID 24533077, 2014). "Elevated levels of inflammatory mediators such as C-reactive protein, interleukin-6, and tumor necrosis factor-α contribute to endothelial dysfunction, promote lipid deposition, and accelerate atherogenesis." (PMID 41598548, 2026). "The most accurate prediction of severe acute pancreatitis is achieved when IL-6 and Ang-2 are used in combination, capturing both systemic inflammation and endothelial dysfunction." (PMID 41590239, 2026). "Circulating biomarkers reflecting systemic inflammation (IL-6) and endothelial dysfunction (Ang-2) have emerged as promising tools for improving early prediction of persistent organ failure and other adverse outcomes." (PMID 41590239, 2026). "In all available head-to-head studies, Ang-2 performed at least as well as IL-6 and frequently exceeded it in terms of AUC, sensitivity and specificity, underscoring its central role as a marker of endothelial dysfunction and microvascular injury." (PMID 41590239, 2026). "In the context of ISR, monocytes activate the vascular endothelium by secreting pro-inflammatory cytokines (e.g., TNF-α and IL-6), promoting endothelial dysfunction and smooth muscle cell proliferation, ultimately leading to vascular remodeling and restenosis." (PMID 41602327, 2026). "Periodontitis triggers systemic release of inflammatory mediators such as C-reactive protein, interleukin-6, and tumor necrosis factor-α, all of which are established contributors to endothelial dysfunction and atherosclerosis." (PMID 41598548, 2026). "Concurrently, hepatocyte-derived pro-inflammatory cytokines (e.g., TNF-α, IL-6) and pro-atherogenic lipoproteins are known to propagate endothelial dysfunction, thereby fostering a ‘hepato-cardio–renal axis’ of injury." (PMID 41449278, 2025). "IL-1β and IL-6 are key drivers of endothelial dysfunction and plaque destabilization, while TNF-α is involved in amplifying the inflammatory cascade and enhancing cellular adhesion, making them particularly relevant therapeutic targets." (PMID 40727466, 2025). "Cytokines such as IL-6 are central to this process and contribute to vascular injury and endothelial dysfunction." (PMID 41254792, 2025).
endothelial dysfunction (continued). "Stronger evidence supports the role of periodontal inflammation and oral microbiota dysbiosis in systemic inflammatory burden, with elevated mediators such as CRP, IL-6, TNF-α, and IL-1β implicated in endothelial dysfunction and atherogenesis." (PMID 41294894, 2025). "Superantigens bypass normal antigen presentation by linking MHC class II molecules with T-cell receptors, causing massive cytokine release (IL-1, IL-2, TNF-α, IL-6, and IFN-γ), endothelial dysfunction, and multiorgan injury." (PMID 41294916, 2025). "Mechanistically, IL-6 promotes endothelial dysfunction, smooth-muscle proliferation, and thrombogenic remodeling through JAK/STAT3 signaling, all of which contribute to plaque instability and restenosis after CEA." (PMID 41440557, 2025). "Persistent endothelial dysfunction and elevated inflammatory markers (IL-6, TNF-α) have been documented in long COVID patients for at least 6 months post-infection." (PMID 41471341, 2025). "IL-6, another pleiotropic cytokine elevated in various cardiometabolic disorders, exacerbates endothelial dysfunction by increasing vascular permeability, promoting leukocyte recruitment, and perpetuating inflammatory signaling cascades." (PMID 41155389, 2025). "In CKD, chronic inflammation activates pro-inflammatory pathways, including nuclear factor-kappa B (NF-κB) and interleukin-6 (IL-6) signaling, driving oxidative stress and endothelial dysfunction." (PMID 41254862, 2025). "Influenza infection triggers a surge in cytokines like IL-1β, IL-6, and TNFα, which contribute to endothelial dysfunction, increased monocyte recruitment, and macrophage infiltration into plaques, making them more prone to rupture." (PMID 41439053, 2025). "In acute phase and in the CCC, IL-6 has long been recognized as a mediator of inflammatory cardiomyopathy, as well as, a promoter of endothelial dysfunction and myocardial fibrosis, which culminate in HF." (PMID 40356773, 2025). "These cascades result in increased transcription of pro-inflammatory cytokines (e.g., TNF-α, IL-6, IL-1β), endothelial dysfunction, and leukocyte recruitment, which together exacerbate tissue inflammation and injury." (PMID 40926894, 2025). "Subsequently, adipose tissue secretes pro-inflammatory cytokines such as TNF-α, IL-6, and resistin, while reducing protective adipokines like adiponectin, contributing to IR, endothelial dysfunction, and systemic inflammation, a process termed metaflammation." (PMID 40959347, 2025). "In the context of IR, adipose tissue produces increased levels of pro-inflammatory mediators like TNF-α and IL-6, which can worsen endothelial dysfunction and accelerate vascular calcification." (PMID 40421241, 2025). "The release of pro-inflammatory cytokines such as interleukin-6 (IL-6) and tumor necrosis factor-alpha plays a critical role in this process, as these cytokines can exacerbate endothelial dysfunction and promote further inflammatory responses." (PMID 41312141, 2025). "In particular, oxidative stress and the chronic release of inflammatory cytokines, especially TNF-α and IL-6, promote extensive endothelial dysfunction in axSpA patients." (PMID 40075844, 2025). "Secondly, HTNpatients are often in a state of persistent low-grade inflammation, and anemiainduces the production of inflammatory cytokines [interleukin (IL)-1, IL-6, andtumor necrosis factor-alpha], which lead to endothelial dysfunction and pooroutcomes." (PMID 40160578, 2025). "IL-6 is a pro-inflammatory cytokine that plays a crucial role in amplifying vascular inflammation and endothelial dysfunction." (PMID 40217801, 2025). "The current body of evidence reveals several consistent patterns, most notably the strong association between chronic periodontal inflammation and systemic endothelial dysfunction, mediated by proinflammatory cytokines such as IL-6, TNF-α, and CRP." (PMID 41294894, 2025).
endothelial dysfunction (continued). "Adipose tissue releases pro-inflammatory cytokines (TNF-α, IL-6, MCP-1), causing endothelial dysfunction, vascular permeability, and tubular injury, leading to nephron loss." (PMID 40136609, 2025). "Visceral adipose tissue secretes bioactive molecules such as tumor necrosis factor-α (TNF-α), interleukin-6 (IL-6), and angiotensinogen, which collectively promote vascular inflammation, endothelial dysfunction, and increased arterial stiffness." (PMID 40703406, 2025). "Experimental and clinical data demonstrate that sustained IL-6 expression correlates with glomerulosclerosis, endothelial dysfunction, and declining eGFR." (PMID 41154568, 2025). "LOX exacerbates vascular inflammation and endothelial dysfunction by activating the nuclear factor-κB (NF-κB) pathway, culminating in the secretion of pro-inflammatory cytokines, including interleukin-6 (IL-6) and tumor necrosis factor-α (TNF-α)." (PMID 40661776, 2025). "Cytokines such as interleukin (IL)-6, tumor necrosis factor-alpha (TNF-α), and IL-1β have been implicated in the inflammatory cascade, leading to endothelial dysfunction and myocardial stress, thereby increasing the susceptibility to arrhythmias." (PMID 40151738, 2025). "Systemic inflammation serves as the key link between the two, with elevated biomarkers such as C-reactive protein and interleukin-6 observed in individuals with PD, driving endothelial dysfunction and atherogenesis." (PMID 40722588, 2025). "This indicates that the induction of ICAM-1 and endothelial dysfunction cannot be ascribed to a direct effect of IL-6 but it is rather a long-lasting change." (PMID 40599782, 2025). "This review highlights the main mechanisms linking RA and CVD, including endothelial dysfunction, pro-inflammatory cytokine pathways (IL-1, IL-6, TNF, and JAK-STAT), and the presence of conventional cardiovascular risk factors." (PMID 40283183, 2025). "CRP, produced in the liver in response to IL-6, is not only a marker but also an active participant in endothelial dysfunction, promoting monocyte adhesion and plaque progression." (PMID 41007869, 2025). "For instance, adipose tissue in patients with SO secretes excessive proinflammatory cytokines, such as tumor necrosis factor-alpha (TNF-α) and interleukin-6 (IL-6), contributing to endothelial dysfunction and arterial stiffness." (PMID 40625352, 2025). "Pro-inflammatory cytokines, such as TNF-α and IL-6, induce endothelial dysfunction by reducing nitric oxide (NO) bioavailability, impairing vasodilation, and increasing oxidative stress." (PMID 40137170, 2025). "Endothelial dysfunction induced by cytokines (IL-1, IL-6, TNF-α) increases capillary permeability and interstitial oedema, while activation of the renin-angiotensin-aldosterone system and natriuretic peptides exacerbates venous congestion and organ damage." (PMID 40585555, 2025). "Elevated levels of inflammatory cytokines such as IL-6, TNF-α, and CRP have been associated with cartilage degradation, endothelial dysfunction, and metabolic dysregulation." (PMID 40843198, 2025). "Once in the bloodstream, LPS triggers systemic inflammation and contributes to endothelial dysfunction by upregulating inflammatory cytokines such as interleukin-6 (IL-6) and tumor necrosis factor-alpha (TNF-α)." (PMID 40361641, 2025). "In addition, pro-inflammatory cytokines (e.g., IL-6 and c-reactive protein) may play a role in the relationship between depressive symptoms and lung function in older adults, causing endothelial dysfunction and reduced alveolar function, promoting the development of COPD." (PMID 40255497, 2025). "Uterine-derived IL-6 contributes to systemic endothelial dysfunction, amplifying vascular pathology." (PMID 40332110, 2025). "IL-6, as a pro-inflammatory cytokine, can directly damage endothelial cells and induce oxidative stress, leading to endothelial dysfunction, aligning with the findings of our research group." (PMID 40041162, 2025).
endothelial dysfunction (continued). "Interleukin-6 (IL-6) is a key cytokine driving vascular inflammation and endothelial dysfunction, serving as a more direct indicator of inflammatory activity than LDL-C alone." (PMID 40217801, 2025). "Serum and CSF biomarkers such as interleukin-6 (IL-6) and endothelin-1 (ET-1) indicate inflammatory and endothelial dysfunction, and they rise days before radiographic or clinical manifestations." (PMID 41194849, 2025). "CRP, produced in the liver under IL-6 stimulation, actively contributes to endothelial dysfunction by enhancing leukocyte adhesion." (PMID 41007869, 2025). "During inflammation, levels of proinflammatory cytokines such as tumor necrosis factor (TNF)-α, interleukin (IL)-6, and IL-1β increase, which trigger apoptosis and fibrosis in cardiomyocytes and contribute to endothelial dysfunction, are increased." (PMID 40004844, 2025). "In AAAD, inflammatory mediators such as interleukin-6 and tumor necrosis factor-α are released by macrophages and neutrophils, promoting extracellular matrix remodeling of vascular walls, endothelial dysfunction, and false lumen formation." (PMID 41285481, 2025). "IL-6 promotes fibroblast proliferation, endothelial dysfunction, and acute-phase reactant synthesis, contributing to systemic inflammation and thrombosis." (PMID 40806851, 2025). "Proinflammatory cytokines such as TNF-α, IL-6, IL-8, and IL-18 contribute to endothelial dysfunction by upregulating adhesion molecules in ECs and leukocytes, thereby promoting leukocyte recruitment and vascular inflammation." (PMID 41155389, 2025). "TNF-α significantly improved the predictive ability of the model, with a hazard ratio (HR) of 2.5 (95% CI: 1.11–6.34; p = 0.01) for MACE in patients with TNF-α ≥ 5.19 pg/mL, even after adjusting for endothelial dysfunction and IL-6." (PMID 40310443, 2025). "In the context of dysfunctional PVAT, IL-6 contributes to the development of oxidative stress and endothelial dysfunction." (PMID 40943241, 2025). "Pro-inflammatory agents like tumor necrosis factor-α (TNF-α), interleukin-6 (IL-6), interleukin-1β (IL-1β), and vascular endothelial growth factors can further exacerbate vascular injury and endothelial dysfunction, leading to vascular remodeling." (PMID 40933377, 2025). "High levels of IL-6 during and after an acute SARS-CoV-2 infection are linked with poor outcomes, such as acute respiratory distress syndrome, myocarditis, endothelial dysfunction, and thrombotic events." (PMID 41472298, 2025). "This venous congestion intensifies endothelial distension, resulting in endothelial dysfunction and the activation of pro-inflammatory cytokines (e.g., IL-6, TNF-α), which exacerbate the systemic inflammatory response syndrome (SIRS) linked to CPB." (PMID 40075778, 2025). "Migraine is increasingly recognized as a neurovascular disorder characterized by episodic endothelial dysfunction, transient inflammatory activation (including interleukin-6 and CRP surges), oxidative stress, and—in many patients—hormonal fluctuations." (PMID 41440551, 2025). "Through JAK/STAT signaling, IL-6 regulates vascular inflammation, endothelial dysfunction, and smooth muscle cell migration, contributing to plaque formation, destabilization, and thrombosis." (PMID 40244022, 2025). "Clinical studies have linked periodontal disease to increased systemic levels of C-reactive protein (CRP), interleukin-6 (IL-6), and endothelial dysfunction, which are known contributors to cardiovascular morbidity." (PMID 40868899, 2025). "Cytokine-mediated inflammation, particularly through TNF-alpha and IL-6, contributes to endothelial dysfunction, hypoxia, and vascular remodelling, ultimately leading to diminished cardiovascular integrity as disease activity increases." (PMID 39891687, 2025).
endothelial dysfunction (continued). "Particularly visceral fat is known to secrete pro-inflammatory cytokines, including tumour necrosis factor-alpha (TNF-alpha) and interleukin-6 (IL-6), which can impede vasodilation and contribute to endothelial dysfunction." (PMID 40108925, 2025). "These compounds attenuate systemic inflammation by lowering circulating levels of C-reactive protein (CRP), interleukin-6 (IL-6), and tumor necrosis factor-α (TNF-α), biomarkers consistently associated with endothelial dysfunction." (PMID 41155474, 2025). "Visceral adiposity is often accompanied by abnormal secretion of pro-inflammatory factors (e.g., tumor necrosis factor alpha, interleukin 6) by adipocytes and increased free fatty acids, which promote endothelial dysfunction and vascular stiffness." (PMID 40778272, 2025). "Elevated LPS enhances monocyte and macrophage activation, inducing pro-inflammatory cytokines (TNF-in IL-6, IL-1,i that aggravate endothelial dysfunction and promote hypertension." (PMID 41503037, 2025). "IL-6 and TNF-α contribute to cardiovascular risk by promoting endothelial dysfunction, oxidative stress, and vascular remodeling." (PMID 40552192, 2025). "Plaque instability, immune cell recruitment, and endothelial dysfunction are all influenced by pro-inflammatory cytokines like IL-6 and TNF-α, as well as pathways including NF-κB, TLRs, and the NLRP3 inflammasome." (PMID 40006011, 2025). "Dysbiosis involving Actinomyces has been associated with increased levels of pro-inflammatory cytokines such as TNF-α and IL-6, which contribute to endothelial dysfunction." (PMID 40005617, 2025). "Gliquidone, known for its antioxidant properties, appears to reverse endothelial dysfunction associated with metabolic actions, controlling LDL cholesterol and IL-6." (PMID 40599143, 2025). "Biomarkers of inflammation and endothelial dysfunction (IL-6, ADMA) are independent predictors of NT-proBNP and provide prognostic value beyond classical determinants." (PMID 41450363, 2025). "IL-6 plays a key role in promoting the release of inflammatory mediators, amplifying the inflammatory response, and contributing to endothelial dysfunction, which accelerates plaque formation and progression." (PMID 40270516, 2025). "In this study, an elevated NLR demonstrated a similar correlation with reduced FMD, a marker of endothelial dysfunction, to that found in other inflammatory markers, such as IL-6." (PMID 40143236, 2025). "Persistent pro-inflammatory cytokines like TNF-α and IL-6 damage vascular endothelial cells, resulting in endothelial dysfunction." (PMID 40313943, 2025). "Its role extends beyond a simple marker of inflammation; in cardiovascular disease, elevated IL‐6 actively promotes endothelial dysfunction, a pro‐coagulant state, and vascular smooth muscle proliferation, as detailed by Hansson GK." (PMID 41307202, 2025). "Cytokines such as interleukin-1, interleukin-6, interleukin-8, interleukin-17, and tumor necrosis factor-alpha are pivotal in BD pathophysiology, promoting a chronic inflammatory state leading to endothelial dysfunction and thrombotic events." (PMID 40823180, 2025). "The cytokine IL-6 promotes the proliferation of smooth muscles in vascular walls, which is an essential aspect in the formation of atherosclerotic plaque and endothelial dysfunction." (PMID 41527594, 2025). "The inflammatory response leads to the release of pro-inflammatory cytokines such as TNF-α, IL-6, and IL-1β, which contribute to endothelial dysfunction and reduced nitric oxide (NO) production, ultimately exacerbating ED development." (PMID 40529500, 2025). "Numerous cohort and meta-analysis studies support a causal or contributory role for H. pylori, particularly via mechanisms such as vascular inflammation, cytokine activation (e.g., TNF-α, IL-6), endothelial dysfunction, and dyslipidemia." (PMID 40893911, 2025).